NRAS (NRAS proto-oncogene, GTPase)
Diseases named in the same sentence as NRAS in open-access papers (continued):
Sharing a sentence is not in itself a finding about the gene and the disease.
myelodysplastic syndrome (20 papers, 2010 to 2025). A clonal hematopoietic disorder characterized by dysplasia and ineffective hematopoiesis in one or more of the hematopoietic cell lines. "Higher PLA2G4A expression results in worse OS and mutations in NRAS, which are known to contribute to the development of myelodysplastic syndrome development." (PMID 38022627, 2023). "Along these lines, recent work evaluating the role of gene mutations on the prognosis of myelodysplastic syndromes demonstrated that patients with mutations in KRAS or NF1 show worse OS than patients with NRAS or CBL mutations." (PMID 29259247, 2017). "Significantly, RAS mutations, usually in KRAS and NRAS, are also frequent events in myeloid malignancies, and have been detected in 3% to 40% of myelodysplastic syndrome (MDS) and AML." (PMID 29029494, 2017). "After that, in 1994, cancer-specific DNA mutations in NRAS (myelodysplastic syndrome (MDS)) and KRAS (pancreatic cancer) were found in the blood of cancer patients." (PMID 27128908, 2016). "Activating mutations in either NRAS or KRAS genes occur in AML, juvenile myelomonocytic leukaemia (JMML), chronic myelomonocytic leukaemia (CMML), childhood ALL and myelodysplastic syndromes (MDS)." (PMID 29940987, 2018). "In another patient with AML, which likely evolved from a myelodysplastic syndrome (MDS), the MDS and secondary AML samples shared a mutation in IDH1 and the AML gained additional mutations only in NRAS and WT1 genes." (PMID 29312904, 2017). "Of these non-JAK2 mutation cases, the NRAS, CSF3R and TET2 c.4319_4329del; p.Arg1440Hisfs*34 were in the context of therapy-related disease; the remaining 4 other mutations (TET2, TET2, DNMT3A, and SF3B1) were in the context of disease progression from myelodysplastic syndrome." (PMID 36323674, 2022).
myeloid neoplasm (20 papers, 2015 to 2026). Proliferation of myeloid cells originating from a primitive stem cell. "Around 10–30% of myeloid malignancies have NRAS variants associated with an aggressive disease, presenting increased proliferation and resistance to therapies." (PMID 40725152, 2025). "Pathogenic variants specific for MDS‐type myeloid neoplasms were found by NGS in the NRAS, U2AF1 and ZRSR2 genes with VAFs of 40%, 24% and 6%, respectively." (PMID 40066790, 2025). "The co-occurrence of U2AF1 and signaling gene mutations also differed across myeloid neoplasms, with NRAS and FLT3 mutations being more common with S34 mutations and CBL, PTPN11 and CSF3R mutations more common with R156/Q157 mutations." (PMID 40386435, 2025). "Oncogenic NRAS mutations are frequently reported in myeloid neoplasms associated with monocyte lineage involvement." (PMID 37841434, 2023). "In myeloid neoplasms, NRAS mutations have been associated with the development of AML (7–13%) secondary to different subtypes of MPN; however, it remains unclear whether these mutations directly promote progression to leukaemia." (PMID 35626091, 2022). "Isolated isochromosome 17q, i(17q), accounts for less than 1% of myeloid neoplasms, including AML, MDS, and myeloproliferative neoplasms (MPN), and frequently harbors mutations in SETBP1, ASXL1, SRSF2, and NRAS." (PMID 41148513, 2026). "NRAS and KRAS activating point mutations are present in 10–30% of myeloid malignancies and are often associated with a proliferative phenotype." (PMID 38658558, 2024). "In this study, we uncovered a previously unappreciated role for RAB27B in regulating NRAS palmitoylation, subcellular trafficking, and signaling in myeloid malignancies, in part via interacting with the palmitoyl acyltransferase ZDHHC9." (PMID 37317963, 2023). "ASXL1mt in myeloid neoplasms were considered to be ubiquitously accompanied by mutations of RUNX1, SRSF2, STAG2, NRAS, or IDH2, in addition to wild‐type NPM1 and FLT3,14, 21, 22, 28 which was aligned with the mutation profile in our cohort." (PMID 38146893, 2023). "To confirm our studies using mutant NRASQ61R, we examined the effect of RAB27B in NRASG12D, the most common mutant form of NRAS in human myeloid malignancies." (PMID 37317963, 2023). "Ren and colleagues have discovered a role of the CBL/JAK2/RAB27B/ZDHHC9 signaling axis in regulating NRAS trafficking to the plasma membrane for activation by palmitoylation in myeloid malignancies." (PMID 37317974, 2023). "Genes associated with methylation and myeloid neoplasms, including DNMT3A and NRAS, were more commonly mutated in T-ALL with CDKN2B hypermethylation." (PMID 30635552, 2019). "In phase I/II trials, trametinib showed evidence of achieving a clinical response in myeloid malignancies associated with NRAS mutations, but not including aCML." (PMID 35949766, 2022).
rectal cancer (20 papers, 2013 to 2026). A primary or metastatic malignant neoplasm that affects the rectum. "We therefore investigated whether deep learning–based segmentation is feasible in predicting KRAS/NRAS/BRAF mutations of rectal cancer using MR-based radiomics." (PMID 34395262, 2021). "However, the role of KRAS or NRAS mutations in localized rectal cancer is uncertain." (PMID 27655166, 2016). "Mutually exclusive KRAS and NRAS mutations were identified, with recurrent activating mutations observed commonly in colon and rectal carcinoma (COAD/READ) (30%, 5%, and 5% for KRAS (Gly 12), KRAS (Gly 13), and NRAS (Gln 61), respectively)." (PMID 38920700, 2024). "Current research on radiomics in rectal cancer mainly focuses on predicting aspects such as complete remission after neoadjuvant therapy for advanced rectal cancer, lymph node metastasis, KRAS/NRAS gene mutations, and microsatellite instability (MSI)." (PMID 37941552, 2023). "A number of studies suggest that glucose accumulation in PET/CT is significantly associated with genetic mutations (KRAS, KRAS/BRAF, or KRAS/NRAS) in primary CRC, metastatic CRC, or rectal cancer." (PMID 34239564, 2021). "Additionally, the rectal cancer exhibited proficient DNA mismatch repair (pMMR) status, ERBB2 copy number amplification, and a missense mutation, while the KRAS, NRAS, and BRAF genes were wild-type." (PMID 39985003, 2025). "Additionally, identification of somatic mutations of KRAS, NRAS, and BRAF genes were performed by direct sequencing and pyrosequencing in pretreated biopsy tissues from 57 patients diagnosed for rectal cancer." (PMID 31998419, 2020). "KRAS/NRAS/BRAF mutations were not significantly related to patients' age analyzed by Student's t-test in rectal cancer." (PMID 30416987, 2018). "There is no information on whether this subgroup of rectal cancer patients have a different prognosis compared to patients with activating mutations nor if absence of mutation in KRAS or NRAS is predictive of response to standard radiochemotherapy." (PMID 27655166, 2016). "In this study, 3D V-Net architecture provided reliable rectal cancer segmentation on T2WI and DWI compared with expert-based segmentation, and auto segmentation was subjected to radiomics analysis in the prediction of KRAS/NRAS/BRAF mutation status and may produce a good prediction result." (PMID 34395262, 2021). "In this study, we segmented rectal cancer via 3D V-Net on T2WI and DWI and then compared the radiomics performance in predicting KRAS/NRAS/BRAF status between DL-based auto segmentation and manual-based segmentation." (PMID 34395262, 2021). "Thus, we attempt to segment rectal cancer via 3D V-Net on T2WI and DWI and then compare the performance of radiomics in predicting the KRAS/NRAS/BRAF status between DL-based auto segmentation and manual-based segmentation." (PMID 34395262, 2021). "The trial is designed to include an enriched population of patients with KRAS and NRAS wild-type rectal cancer due to evidence of lack of benefit from anti-EGFR strategies in KRAS or NRAS mutated colorectal tumors." (PMID 27655166, 2016).
rectal cancer (continued). "However, this relationship between NRAS gene mutations and C-MET expression was not yet observed for CRCs, presumably because of analyzing CRCs without distinguishing and focusing on those that overexpress NRAS, such as in rectal cancer." (PMID 41563267, 2026).
adenoma (19 papers, 2009 to 2025). A neoplasm arising from the epithelium. "Two high-risk cases were distinguished by the presence of BRAF p.V600E and PIK3CA p.E545K mutations, whereas one adenoma of the low-risk cases showed NRAS p.G12D." (PMID 34372923, 2021). "NRAS has previously been reported to be more frequent in carcinomas (24%) than adenomas (14%), and significantly associated with mortality." (PMID 31248021, 2019). "One study has investigated NRAS mutation frequency in a very small series of flat adenomas showing a percentage of 25% (2 out of 8 samples)." (PMID 22848674, 2012). "In the COSMIC database 2.8% NRAS mutations have been reported in adenomas (based on 142 samples)." (PMID 22848674, 2012). "Most biomarkers for the outcome of adenocarcinoma used in histology are related to the adenoma-carcinoma pathway and show mutations in oncogenes such as KRAS, NRAS, BRAF, APC, and DDF." (PMID 38187473, 2023). "Eleven somatic mutations were located in genes involved in the early adenoma formation (APC, RNF43 and CTNNB1), whereas two mutations were detected in genes involved in later stages (ARID1A, NRAS)." (PMID 31285513, 2019). "Presence of APC, KRAS, NRAS, and GNAS mutations in HGCA well matched ‘classical adenoma-carcinoma model’." (PMID 28179590, 2017). "Our HGCA mutation list includes not only those in this classical model (APC and KRAS) but also those already known as adenoma genes (NRAS and GNAS)." (PMID 28179590, 2017). "Moreover, the exclusive occurrence of an NRAS mutation in FTC, shown also in other studies, indicates that the diagnosis of adenoma alongside the presence of this mutation should be made cautiously." (PMID 31248021, 2019). "Recently, ACF were identified in the proximal colons of about 40% of individuals undergoing high-resolution chromoendoscopy and more frequently in patients with synchronous proximal adenomas; somatic mutations of APC, BRAF, KRAS, NRAS and ERBB2 were detected in 37% of proximal ACF." (PMID 29652830, 2018). "NRAS mutation does not seem to affect the early phases of tumor progression and the adenoma–carcinoma sequence, but it might inhibit epithelial cells’ stress‐induced apoptosis." (PMID 28378457, 2017). "RAS (including KRAS, NRAS, and HRAS) molecular alterations are most frequently seen in follicular carcinomas and benign adenomas." (PMID 39456540, 2024). "Chung and colleagues found increased adenoma-to-carcinoma conversion with SHH transgene-induced injury, while Dauch and colleagues found that CCl4 could overcome NRas-induced p19Arf tumor suppressor activity, to increase tumor burden." (PMID 39254423, 2024).
colorectal tumors (19 papers, 2015 to 2025). "Mutation profiles for KRAS/NRAS have previously been shown to be highly concordant between samples from the same colorectal tumor." (PMID 33014822, 2020). "Testing for NRAS mutations is now a standard of care in KRAS wild-type colorectal tumors." (PMID 29682098, 2018). "In summary, our study presents a promising treatment strategy for patients with wild-type KRAS/NRAS/BRAF colorectal tumors." (PMID 39905540, 2025). "To date, liquid biopsies have shown the selective pressure of anti-EGFR therapies in patients with RAS-wild-type * colorectal tumors, in that acquired resistance to EGFR blockade is often driven by the emergence of KRAS/NRAS mutations in plasma." (PMID 35159069, 2022). "Four hundred fourteen colorectal tumors were screened for KRAS and NRAS mutations." (PMID 37277698, 2023). "Furthermore, mutations in KRAS, NRAS, and BRAF are mutually exclusive in colorectal tumours, and it has been reported that patients with BRAF and NRAS modifications have considerably shorter survival rates." (PMID 36612217, 2022). "Transcriptomic profiling of NSCLC and CRC cases may serve to further confirm the correlation between circPVT1 and NRAS expression in lung and colorectal tumors." (PMID 33907219, 2021). "Arbitrary selected 75 colorectal tumors were analyzed for BRAF, KRAS, and NRAS gene mutations." (PMID 28460459, 2017). "Up to 60% of colorectal tumors exhibit gain-of-function mutations in KRAS, NRAS and BRAF genes." (PMID 27582544, 2016). "The same experimental strategy was then applied to an independent PDX that was also derived from a quadruple wild-type (KRAS, NRAS, BRAF and PIK3CA) colorectal tumour and was sensitive to EGFR blockade." (PMID 26392303, 2015). "This was derived from an individual carrying a quadruple wild-type (KRAS, NRAS, BRAF and PIK3CA) colorectal tumour, and thus recapitulates the molecular profile of patients sensitive to anti-EGFR antibodies." (PMID 26392303, 2015).
follicular thyroid carcinoma (19 papers, 2016 to 2025). "The presence of a NRAS mutation on tumor genomic profiling further supports the interpretation that this tumor represented a poorly differentiated carcinoma arising from follicular thyroid carcinoma." (PMID 41322887, 2025). "Mutations in the NRAS gene (1p13.2), which encodes the NRAS protein (189 amino acids; 21,229 Da), are associated with Noonan and autoimmune lymphoproliferative syndromes, rectal somatic and follicular thyroid cancers, and juvenile myelomonocytic leukemia." (PMID 37509254, 2023). "Patient FNA-0330, who has three mutations (BRAF V600E/NRAS Q61R/AKT1), was confirmed as follicular thyroid carcinoma (FTC) with lymph node metastasis." (PMID 40586006, 2025). "It has been shown that mutations in the RAS family genes (NRAS, KRAS, HRAS) are most commonly associated with follicular thyroid carcinoma (FTC), but they are also present in three other types, including anaplastic thyroid cancer (ATC)." (PMID 39767735, 2024). "Gene alterations in follicular thyroid carcinoma include point mutations in HRAS, NRAS, and KRAS genes." (PMID 36607876, 2023). "NRAS, HRAS, and KRAS mutations, which are seen in 30–50% of follicular thyroid cancer (FTC), were detected in 8% of classic and in 33% of follicular variant PTCs." (PMID 34630336, 2021). "Transgenic mice with human NRAS oncogene expression in the thyrocytes under the control of Tg promoter (Tg-NRAS) developed thyroid adenomas (11%) and invasive follicular carcinomas (40%), with approximately 25% showing poor differentiation, lymphovascular invasion and increased metastatic risk." (PMID 34062862, 2021). "We analyzed the profile of 53BP1 expression and NRAS codon 61 and TERT-promoter (TERT-p) mutations in 16 cases of TFTs showing NN with PDc compared to 30 adenomatous goiters, 31 follicular adenomas, 15 minimally invasive follicular carcinomas (FCs), and 11 widely invasive FC cases." (PMID 35892838, 2022).
lymphoma (18 papers, 2011 to 2025). A malignant (clonal) proliferation of B- lymphocytes or T- lymphocytes which involves the lymph nodes, bone marrow and/or extranodal sites. "Consistent with the suppression of apoptosis by senescence, the loss of Suv39h1 and therefore of OIS competence renders NRas‐driven lymphomas responsive to apoptosis induction." (PMID 32981205, 2021). "Expressing NRAS(G12D) alone using our conditional retroviral expression system limiting NRAS(G12D) to developing T cells caused a mature T-cell leukemia/lymphoma characterized by thymus enlargement." (PMID 34230493, 2021). "Compared to the lymphoma group, the protein quantitative analysis of the LGBLEL group exhibited significantly differentially expressed CCL28, CCR1, CXCL17, HCK, GNB5, NRAS, and VAV2 (p = 0.003, 0.011, 0.001, 0.024, 0.005, 0.019, and 0.031, respectively)." (PMID 39451532, 2024). "In this study, key genes from the chemokine signaling pathway—HCK, GNB5, NRAS, and VAV2—were validated, confirming their differential expression between LGBLEL and lymphoma and suggesting their important role in the malignant transformation of LGBLEL." (PMID 39451532, 2024). "RT-qPCR showed that, compared to the lymphoma group, the LGBLEL group had significantly higher expression of CCL28, CXCL17, HCK, GNB5, NRAS, and VAV2 (p = 0.001, <0.001, <0.001, <0.001, =0.020, <0.001, respectively) and lower expression of CCR1 (p = 0.002)." (PMID 39451532, 2024). "Compared to the lymphoma group, the LGBLEL group exhibited higher expression levels of CCL28, CXCL17, HCK, GNB5, NRAS, and VAV2 (p = 0.001, <0.001, <0.001, <0.001, 0.020, and <0.001, respectively) and lower expression of CCR1 (p = 0.002)." (PMID 39451532, 2024). "WB revealed that, compared to the lymphoma group, the LGBLEL group exhibited significantly higher expression of CCL28, CXCL17, HCK, GNB5, NRAS, and VAV2 (p = 0.012, 0.005, 0.009, 0.011, 0.008, and 0.003, respectively) and lower expression of CCR1 (p = 0.014)." (PMID 39451532, 2024). "Compared to the lymphoma group, the LGBLEL group showed higher expression of CCL28, CXCL17, HCK, GNB5, NRAS, and VAV2 (p = 0.012, 0.005, 0.009, 0.011, 0.008, and 0.003, respectively) and lower expression of CCR1 (p = 0.014)." (PMID 39451532, 2024). "Other studies have also shown that overexpression of NRAS promotes the development of lymphomas that are however induced by the use of chemical agents, not just overexpression of the RAS gene." (PMID 35120522, 2022).